HBA2 (hemoglobin subunit alpha 2)
Diseases named in the same sentence as HBA2 in open-access papers (continued):
Sharing a sentence is not in itself a finding about the gene and the disease.
Hypertension (5 papers, 2014 to 2024). The presence of chronic increased pressure in the systemic arterial system. "The annotation of DEGs in RGD (Rat Genome Database) revealed 18 genes associated with hypertension, and according to DAVID, four additional DEGs (Acta2, Hba2, P2rx4, and Sult1a1) were defined as related to regulation of BP." (PMID 32039698, 2019). "HBA2 and HBA1 have a key role in hypertension, but these genes might be linked with development HF." (PMID 34218797, 2021). "In the RNA-Seq dataset, the identification of four DEGs related to regulation of BP, namely Guca2b, Hmox1, Hba2, and Hba-a2, is of particular interest for elucidating possible mechanisms by which l-NAME and/or l-citrulline medicates programmed hypertension." (PMID 25517031, 2014).
G6PD deficiency (4 papers, 2022 to 2025). An X-linked genetic condition caused by alterations in the gene G6PD that result in moderately to severely decreased activity levels of the enzyme glucose-6-phosphate dehydrogenase. "The blood work revealed G6PD deficiency and a variant hemoglobin present on electrophoresis, with elevated HbA2 suggestive of an unstable beta-globin variant." (PMID 41306179, 2025). "Although there appears to be no direct correlation between risperidone therapy and low oxygen saturation, the index patient had hematological features, namely G6PD deficiency and elevated HbA2, that could contribute to low oxygen saturation." (PMID 41306179, 2025). "Donor G6PD deficiency and polymorphisms in SEC14L4, HBA2, and MYO9B genes were associated with decreased hemoglobin increments." (PMID 34793330, 2022). "Therefore, we present a rare case of low oxygen saturation in a patient with glucose-6-phosphate dehydrogenase (G6PD) deficiency and variant hemoglobin (elevated HbA2) on risperidone therapy, who exhibited no respiratory compromise." (PMID 41306179, 2025).
erythrocytosis (3 papers, 2021 to 2022). "Up to now, two types of erythrocytosis have been associated with mutations in hemoglobin genes, HBA1, HBA2 (ECYT7) and HBB (ECYT6) respectively, however hemoglobin variants do have diverse pathophysiology." (PMID 34440324, 2021). "Therefore, we recommend the systematic sequencing of the HBB, HBA1 and HBA2 genes in the exploration of idiopathic erythrocytosis." (PMID 35052472, 2022). "We sequenced the HBB, HBA1 and HBA2 genes of 75 patients with idiopathic erythrocytosis." (PMID 35052472, 2022). "The HBB, HBA1 and HBA2 genes were not part of our initial NGS panel since in our initial diagnostic strategy, blood gases were performed as part of the screening workup for erythrocytosis." (PMID 35052472, 2022).
lung carcinoma (3 papers, 2016 to 2024). "Both HBB and HBA2 are shown to potentially impact the progression of nonsmall cell lung cancer." (PMID 39495117, 2024). "In lung cancer, the five most important mRNAs were HBB, HBA2, MT2A, ZFP36, and DUSP1." (PMID 39495117, 2024).
bipolar disorder (2 papers, 2009 to 2014). A disorder of the brain that causes unusual shifts in mood, energy, activity levels and the ability to carry out day-to-day tasks. "Human HbA2 and HbF were associated with disease severity in bipolar disorder with a likely protective role of HbA2 against post-partum episodes." (PMID 25472829, 2014).
hydrops fetalis (2 papers, 2024 to 2025). Hydrops fetalis is a severe and challenging fetal condition usually defined as the excessive accumulation of fetal fluid within the fetal extravascular compartments and body cavities that manifests as edema, pleural and pericardial effusion and ascites. "In alpha-thalassemia, the common mutation types are often deletions affecting one or more of the alpha-globin genes (HBA1 and HBA2) or one pseudogene with a homozygous configuration of the allele, which results in the hydrops fetalis form." (PMID 40523316, 2025). "No PCR product from the HBA2 and HBA1 genes was obtained from the Bart’s hydrops fetalis (--SEA/--SEA) sample." (PMID 38961367, 2024).
Insulin resistance (2 papers, 2022 to 2023). Increased resistance towards insulin, that is, diminished effectiveness of insulin in reducing blood glucose levels. "In this sense, we have found an upregulation of different genes related to hypoxia regardless of the degree of insulin resistance, such as ANGPTL4, LPL, S100A8, SLC11A2, HBB, HBA2, and HBD." (PMID 35625760, 2022).
osteosarcoma (2 papers, 2019 to 2024). A usually aggressive malignant bone-forming mesenchymal neoplasm, predominantly affecting adolescents and young adults. "Similarly, HBA1, HBA2, and HBB were downregulated in osteosarcoma samples." (PMID 38966281, 2024).
prion disease (2 papers, 2014 to 2022). A transmissible disease that is caused by a protein that is able to induce abnormal folding of normal cellular proteins, leading to characteristic spongiform brain changes, which are associated with neuronal loss without an inflammatory response. "Subsequent studies found that HBA2 was downregulated in cattle infected with atypical Bovine Spongiform Encephalopathy infected cattle, and reduced expression of several other erythroid genes, Kell, GPA, band 3, and ankyrin were observed in mice with prion disease." (PMID 35237232, 2022).
pterygium (2 papers, 2020 to 2021). A wedge-shaped fibrovascular lesion arising from the bulbar conjunctiva and extending to the cornea. "From the results of RNA-Seq, LCN1, LTF, SCGB2A1, HBA1 (hemoglobin subunit alpha 1) and HBA2 (hemoglobin subunit alpha 2) ranked as the top five DEGs in the comparison between pterygium and normal tissues." (PMID 32411530, 2020). "In this study, HBA1, HBA2, and HBB were among the top 25 upregulated DEGs in pinguecula and top 25 downregulated DEGs in pterygium." (PMID 34769520, 2021). "For example, hemoglobin genes HBA1, HBA2, and HBB were among the top 25 upregulated genes in pinguecula and top 25 downregulated genes in pterygium." (PMID 34769520, 2021). "The mRNA expressions of SCGB2A1, LTF and LCN1 were significantly decreased in pterygium tissues compared with normal control tissues, while the mRNA levels of HBA1 and HBA2 were higher in the pterygium tissues than in the control tissues." (PMID 32411530, 2020).
abdominal aortic aneurysm (1 paper, 2023). Enlargement and ballooning of the vessel that supplies arterial blood to the abdomen, pelvis and legs. "HBA1 and HBA2 both encode alpha subunits of hemoglobin and have also been found to be increased in abdominal aortic aneurysms." (PMID 36836499, 2023). "For example, several (5/39) of the significant genes (including LPL, IFI44L, ACKR2, HBA1, and HBA2) have also been found to be differently expressed in abdominal aortic aneurysms." (PMID 36836499, 2023).
asthma (1 paper, 2021). "In bronchial epithelial cells collected by bronchoscopic brush biopsy, the expression of hemoglobin genes (HBA1, HBA2, HBB and HBD) was strongly correlated with Pre-bronchodilator FEV1 PP in patients with asthma enrolled in SARP I&II but not in controls." (PMID 34326365, 2021).
atherosclerosis (1 paper, 2024). A disease characterized by the build-up of fatty material and calcium deposition in the arterial wall resulting in partial or complete occlusion of the arterial lumen. "Finally, miR-199b-5p upregulation was predicted to lead to the activation of HbA1c (HBA1/HBA2) through the inhibition of surfactant protein A1 (SFTPA1), thus resulting in a predicted association with enhanced atherosclerosis progression." (PMID 39125657, 2024).
avian influenza (1 paper, 2020). Infection of domestic and wild fowl and other birds with influenza A virus. "In conclusion, HBA1 and HBA2 can be used to diagnose avian influenza in place of traditional diagnostic methods, because they can quickly and accurately distinguish between the avian influenza subtypes." (PMID 32731467, 2020).
cervical cancer (1 paper, 2016). A primary or metastatic malignant neoplasm involving the cervix. "Next, we checked the Cervical Cancer Database (CCDB) and found three genes, haemoglobin alpha 2 (HBA2), mesothelin (MSLN) and STK11, overlapped between 849 genes/loci observed from our current study and 538 genes listed in the CCDB." (PMID 29083376, 2016).
deficiency anemia (1 paper, 2022). "HbA2 levels can also be affected by iron status, whereas in deficiency anemia, HbA2 levels will decrease." (PMID 35573052, 2022).
endometriosis (1 paper, 2024). The growth of functional endometrial tissue in anatomic sites outside the uterine body. "In the high JUP group, we identified several downregulated genes in the PBMCs from endometriosis patients, including HBB, HBA1, HBA2, RGPD2, CH25H, LTB, IFIT2 and JUN." (PMID 39684780, 2024). "Comparison between participants without endometriosis (n = 5) and participants with endometriosis (n = 4) with high serum JUP values (>220 ng/mL) identified nine DEGs (HBB, HBA1, HBA2, and RGPD2 in CD14+ monocytes; CH25H, HBB, LTB, and KLRC1 in γδt; IFIT2 in NK-CD56bright and JUN in Treg)." (PMID 39684780, 2024).
Fibroadenoma (1 paper, 2020). A benign tumor of the breast characterized by the presence of stromal and epithelial elements. "Furthermore, the expression of seven step-changing proteins (KRT10, KRT1, KRT6E, PLIN1, HBA2, FHL1, and ME2) were decreased in fibroadenoma tissues compared to fibroadenoma adjacent and normal tissues." (PMID 33194682, 2020).
fibrosis (1 paper, 2019). the formation of excess fibrous connective tissue in an organ or tissue in a reparative or reactive process. "We validated the up‐regulation of UBE2V1, BNIP3L mRNAs, RP11‐128N14.5 lncRNA, TGFB2/TGFB2‐OT1 coding/lncRNA in patients with NAS ≥ 5 (vs NAS ≤ 4) and the up‐regulation of HBA2 mRNA, TGFB2/TGFB2‐OT1 coding/lncRNA in patients with Fibrosis stages = 3‐4 (vs F = 0‐2)." (PMID 31169972, 2019).
hypothyroidism (1 paper, 2020). Abnormally low levels of thyroid hormone. "In addition, the volumes of blood collected did not allow us to refine our screening strategy to take account of data from complete blood counts or to investigate children for alternative causes of raised HbA2 values, which include megaloblastic anemia, HIV infections, and hypothyroidism." (PMID 32394645, 2020). "This could be explained by the presence of rare pathogenic variants in the δ‐globin gene or by other causes of elevated HbA2, which include megaloblastic anemia, HIV infections, and hypothyroidism, none of which we investigated in the current study." (PMID 32394645, 2020).
methemoglobinemia (1 paper, 2023). An inherited or acquired condition characterized by abnormally increased levels of methemoglobin in the blood. "HbF was 1.5% (normal 0.8–2%), HbA2 as 3.1% (normal 2.0–3.5%), while MetHb was 50.5% manifesting congenital methemoglobinemia." (PMID 36837579, 2023).
multiple sclerosis (1 paper, 2020). A progressive autoimmune disorder affecting the central nervous system resulting in demyelination. "In addition, we show that HbA2 is significantly increased in patients with multiple sclerosis under type 1 interferon treatment." (PMID 32528964, 2020). "With the aim of verifying whether the use of type I interferon was able to modify the expression of HbA2 in humans, we conducted a study in patients with multiple sclerosis (MS) who underwent therapy with IFNb." (PMID 32528964, 2020).
multiple system atrophy (1 paper, 2017). Multiple system atrophy (MSA) is a neurodegenerative disorder characterized by autonomic failure (cardiovascular and/or urinary), parkinsonism, cerebellar impairment and corticospinal signs with a median survival of 6-9 years. "In addition to PD, altered expression of hemoglobin genes, including HBB, HBA1, and HBA2 have been found in the frontal cortex of multiple system atrophy patients, an atypical parkinsonian disorder that is often misdiagnosed as PD." (PMID 28424608, 2017).
preeclampsia (1 paper, 2025). Preeclampsia is a hypertensive disorder of pregnancy that is characterized by new-onset hypertension with proteinuria presenting after 20 weeks of gestation, and depending on mild or severe forms may initially present with severe headache, visual disturbances, and hyperreflexia. "The mean HbA2 concentration in the preeclampsia group was 0.113 ± 0.31, whereas it was 0.00 ± 0.00 in the control group; however, this difference was not statistically significant." (PMID 40446190, 2025).
viral infections (1 paper, 2022). "It has also been shown that some viral infections can alter the ratio of HbA2, and even the recently prevalent COVID-19 infection can cause changes in HbA2, but the mechanism is not clear." (PMID 36389695, 2022).
Wolman disease (1 paper, 2021). Wolman disease represents the most severe manifestation of lysosomal acid lipase deficiency. "Using a similar Cas9/AAV6 approach, Pavani and colleagues targeted the lysosomal acid lipase (LAL) transgene, associated with the LSD Wolman disease, into the alpha-globin loci (HBA1 and HBA2) of healthy donor HSPCs." (PMID 33535527, 2021).
tumor (5 papers, 2022 to 2024). "Tumor cells expressing the Erythroid-like signature in patients 2 and 5 expressed early-stage erythroblast markers, but had lower expression of mid and late stage erythroid markers HBG1, HBG2, HBA2, and HBB than tumor-associated erythroid cells." (PMID 36008377, 2022). "The genes with the highest log fold-change of expression in the tumor chunks compared to the dissociated cells were hemoglobin genes (HBA1, HBA2, HBB)." (PMID 37864274, 2023). "Furthermore, when comparing T cells from BM with those from primary tumor IV, we observed significant alterations in the expression of genes such as PLP1 (log2FC = 2.34), HSPA1A (log2FC = 2.09), HBB (log2FC = −2.93), and HBA2 (log2FC = −2.44)." (PMID 38612588, 2024). "Due to the tumor-promoted mechanisms of HOXC11 remains unclear, we used GSEA to enrich some HOXC11 expression-related genes, including CCL5, HBA2, and SPHK1, and then detected their mRNA expressive levels in HOXC11 overexpressed cells." (PMID 36823149, 2023). "Because both cancer cohorts have no HGB-related clinical data available, we quantified a tumor’s HGB level as the average expression levels of four HGB-related genes (HBA1, HBA2, HBB and HBD)." (PMID 39415833, 2024).
cancer (3 papers, 2023 to 2025). A tumor composed of atypical neoplastic, often pleomorphic cells that invade other tissues. "First of all, in analyzing the TCGA and Pancancer_2020 cohorts, we have used the mean expression levels of HBA1, HBA2, HBB and HBD to represent HGB levels of cancer patients, which may not fully reflect blood HGB levels." (PMID 39415833, 2024).
infection (3 papers, 2010 to 2022). The state of being infected such as from the introduction of a foreign agent such as serum, vaccine, antigenic substance or organism. "Genes (Hbb-bt, Hba1/Hba2, and Alas2) involved in hemoglobin biosynthesis and heme homeostasis, on the other hand, were significantly down-regulated in response to infection." (PMID 30857242, 2019). "Unsurprisingly, HbA1, HbA2 and HbD gene expression was less in ALV-J infected birds, although until now, little has come to light on the molecular relationship between hemoglobin synthesis and ALV infection." (PMID 21637603, 2010).
neurodegenerative disease (2 papers, 2022 to 2024). A disorder of the central nervous system characterized by gradual and progressive loss of neural tissue and neurologic function. "HBA2 encodes for the hemoglobin subunit alpha-2 chain, whose expression was found to be reduced in the context of several neurodegenerative diseases." (PMID 39456899, 2024). "piR-hsa-2834636 is derived from HBA2, of which the mRNA is dysregulated in the frontal cortex of neurodegenerative disease." (PMID 35269612, 2022).
HBA2 also shares sentences with these, for which no sentence is quoted: diabetes (3 papers); hematological disease (3); microcytic anemia (3); phenylketonuria (3); spinal muscular atrophy (3); beta-thalassemia intermedia (2); breast carcinoma (2); genetic disease (2); Wilson disease (2); adenoma (1); allergic disease (1); Alpha thalassemia major (1); autosomal recessive deafness (1); autosomal recessive disease (1); blood disease (1); chronic lung disease (1); congenital adrenal hyperplasia (1); Congenital hemolytic anemia (1); COVID-19 (1); Crohn disease (1); Cyanosis (1); focal segmental glomerulosclerosis (1); folic acid deficiency (1); haemolytic anaemia (1); hearing loss (1); hepatocellular carcinoma (1); hyperthyroidism (1); hypopharyngeal cancer (1); Impaired glucose tolerance (1); Intellectual disability (1).
A further 18 diseases each share a sentence with HBA2 in 1 paper.